MTOR (mechanistic target of rapamycin kinase)
Diseases named in the same sentence as MTOR in open-access papers (continued):
Sharing a sentence is not in itself a finding about the gene and the disease.
asthma (continued). "Ultimately, control of the balance of MTOR and autophagy may offer a new therapeutic strategy to treat muco-obstructive lung diseases such as asthma." (PMID 40446022, 2025). "Manipulating the balance of MTOR and autophagy may be a therapeutic pathway to pursue in severe asthma." (PMID 40446022, 2025). "However, in the presence of IL-13 activation as a model of severe asthma, MTOR signaling was required for key features of airway mucous cell metaplasia, MUC5AC staining levels, and number of eGC." (PMID 40446022, 2025). "Carbamazepine has been shown to induce antimicrobial autophagy through mTOR-independent pathway, suggesting that autophagy induction by repurposed drug could provide an easily implementable potential therapy for some asthma phenotypes." (PMID 37063888, 2023). "The mTOR signaling pathway participates in the regulation of cell growth and energy metabolism under physiological and pathological conditions; it also plays a crucial role in asthma." (PMID 37181813, 2023). "This study showed that the AMPK/mTOR pathway was modulated in asthma." (PMID 37662894, 2023). "Activation of the mTOR pathway has been shown to lead to tight junction susceptibility and epithelial–mesenchymal transition (EMT), which can in turn play an essential role in airway remolding in asthma pathogenesis." (PMID 35327424, 2022). "Furthermore, the same group showed increased mTOR levels in serum from children with asthma exacerbations compared to patients in asthma remission." (PMID 35720347, 2022). "In ozone-induced exacerbation of asthma, PVT1 activates the asthma-related phosphatidylinositol 3-kinase (PI3K)/AKT/mammalian target of rapamycin (mTOR) pathway by inhibiting miR-15a-5p, leading to a decrease in Th1/Th2 ratio, thereby promoting the progression of asthma." (PMID 35794862, 2022). "Brg1 exacerbates asthma airway inflammation by inhibiting the PI3K/Akt/mTOR pathway." (PMID 35399637, 2022). "Activation of the ROS/PI3K/Akt/mTOR pathway by CSE plays a key role in cell senescence in asthma and may contribute to lung inflammation and alterations in asthma." (PMID 34069141, 2021). "For instance, Xia et al25 reported that interleukin 4 could aggravate asthma through activation the autophagy in pulmonary B cells via regulating mTOR signalling and Ptdlns3K signalling." (PMID 34050597, 2021). "Furthermore, MTOR activation is required for asthma onset, and when MTOR is inhibited pharmacologically, it often induces diarrhea." (PMID 34197453, 2021). "Interestingly, the PI3K-Akt-mTOR signaling counted much in lung inflammation and airway remodeling of asthma, and they were involved in propelling ozone-stimulated oxidative stress." (PMID 33223504, 2020). "It was thus speculated that PVT1-miRNA axis might participate in ozone-induced asthma development by activating PI3K/Akt/mTOR signaling." (PMID 33223504, 2020). "It is therefore clinically beneficial to screen new drugs for asthma that target mTOR signaling." (PMID 30873032, 2019). "Furthermore, aberrant mTOR signaling is involved in the pathogenesis of asthma, and the inhibition of mTOR has been shown to attenuate key characteristics of allergic asthma, including airway inflammation, AHR, and goblet cell metaplasia." (PMID 30873032, 2019). "OVA-challenged mice were treated with 50 mg/kg ketamine alone or in combination with rapamycin to evaluate whether MTOR played a role in a ketamine-mediated protective effect on asthma." (PMID 30729138, 2019). "Additionally, IL-4-induced autophagy in B cells exacerbated asthma through an mTOR-independent, PtdIns3K-dependent pathway." (PMID 31849968, 2019). "The mTOR signaling, including two distinct signaling complexes, mTORC1 and mTORC2, is a central regulator of cell metabolism, growth, proliferation, and survival and is known to play a significant role in the pathogenesis of asthma." (PMID 30873032, 2019). "The effect of mTOR inhibitors on asthma of different subtypes and stages should be investigated." (PMID 28674387, 2017).
asthma (continued). "Therefore, the goal of this study was to confirm antiasthmatic effects of AS-IV in a model of established asthma as well as to investigate the possible mechanisms of AS-IV action, especially with respect to the mTOR signaling pathway." (PMID 29234390, 2017). "This study focused on the role of mTOR in asthma, whether asthma onset could be suppressed by selectively inhibiting mTOR signaling, and a comparison of the effects of inhibitors targeting different molecules in the pathway." (PMID 28674387, 2017). "mTOR has previously been shown to play an important role in the pathogenesis of asthma." (PMID 29234390, 2017). "The mTOR signaling pathway has been demonstrated to play a significant role in the growth and proliferation of Treg cells which have an arsenal of mechanisms in asthma." (PMID 29234390, 2017). "In the asthma remission phase, mTOR, Th17, Treg cells, and their cytokines were restored to similar levels as those in the controls, indicating that inflammation during asthma was suppressed in the asthma remission phase to a level similar to that of the controls." (PMID 28674387, 2017). "The role of mTOR in asthma was further confirmed using an ovalbumin-induced asthmatic mouse model." (PMID 28674387, 2017). "Mice in the asthma group displayed the highest smooth muscles hypertrophy, thickest airway wall, and the most severe basement membrane thickening, which were all significantly improved with mTOR inhibitor treatment." (PMID 28674387, 2017). "However, despite studies supporting the involvement of mTOR in asthma, controversy exists over the effects of rapamycin treatment in asthma, especially its ability to suppress airway inflammation and airway hyperreactivity." (PMID 28674387, 2017). "To determine whether activation of mTOR is required for asthma onset, we examined whether mTOR pathway inhibitors could alleviate asthmatic markers in mice." (PMID 28674387, 2017). "Similarly, mTOR inhibitor treatment during asthma onset restored IL-4, IL-10, and IFN-γ levels to levels similar to those in the control mice." (PMID 28674387, 2017). "To further define the role of mTOR in asthma onset and to validate our observations in human specimens, we established an asthmatic mouse model by treating mice with ovalbumin (OVA)/aluminum, and alleviated their asthma by pre-treating the mice with budenoside." (PMID 28674387, 2017). "This indicates that mTOR in patient serum was positively correlated with asthma disease status." (PMID 28674387, 2017). "Thus, the activation of mTOR by PKC δ prompted us to investigate the functional importance of this relationship in murine models of asthma." (PMID 24312355, 2013). "From these, it is inferred that PKC δ and PI3K/Akt might activate mTOR and p70S6K in an experimental asthma model." (PMID 24312355, 2013). "Recently, inhibition of the mammalian target of rapamycin (mTOR) has been shown to alleviate cardinal asthmatic features, including airway hyperresponsiveness, eosinophilic inflammation, and increased vascular permeability in asthma models." (PMID 24312355, 2013). "Therefore, the inhibition of PKC δ by rottlerin is supposed to attenuate AHR and airway inflammation through suppressing the PI3K/Akt/mTOR/HIF-1α/VEGF pathway in an asthma model." (PMID 24312355, 2013). "The mechanism underlying the paradoxical effects of rapamycin in the induction and treatment models of HDM-induced asthma may in part have reflected the temporal association between HDM challenge and activation of mTOR signaling pathways." (PMID 22685525, 2012). "Thus, the paradoxical effects of rapamycin on asthma severity paralleled the activation of mTOR signaling." (PMID 22685525, 2012). "The objective of this study was to assess whether inhibition of mTOR with rapamycin modifies disease severity in two experimental murine models of house dust mite (HDM)-induced asthma." (PMID 22685525, 2012).
asthma (continued). "In conclusion, our results demonstrate that inhibition of mTOR signaling with rapamycin has paradoxical effects on the pathogenesis of HDM-induced asthma that are dependent upon the temporal relationship between rapamycin administration and the activation of mTOR signaling pathways." (PMID 22685525, 2012). "Taken together, these results demonstrate that inhibition of mTOR signaling by rapamycin represents a “molecular switch” with divergent effects on asthma pathogenesis that are dependent upon the temporal relationship between rapamycin administration and allergen sensitization." (PMID 22685525, 2012). "If validated in human studies, targeting the DC-NK cell metabolic checkpoint with agents that restore autophagic plasticity, rebalance AMPK/mTOR signaling, or normalize airway nutrient and pH landscapes may represent a promising strategy to prevent viral-triggered asthma exacerbations." (PMID 42004956, 2026). "Therefore, the goal of this study was to confirm the anti-asthmatic effects of MSJZT during the remission phase in a murine model of established asthma, and to investigate the possible mechanisms of underlying the action of MSJZT, with particular emphasis on the mTOR signaling pathway." (PMID 30873032, 2019). "However, it remained unclear whether the beneficial effects of AS-IV on asthma were attributed to the mTOR inhibition; this issue was the focus of the present work." (PMID 29234390, 2017). "Similarly, mTOR signaling may modulate angiogenesis and lymphangiogenesis, both of which play important roles in asthma pathogenesis." (PMID 22685525, 2012). "Previous studies have shown that luteolin affects asthma via the induction of FOXP3+ and CD4+CD25+ Tregs or acts as an immunosuppressant mTOR inhibitor to increase the percentage of CD4+FOXP3+ Tregs posttransplantation." (PMID 33532509, 2021). "Dickkopf-1 has been demonstrated to regulate Th2 cell effector functions via the mechanistic target of rapamycin (mTOR) pathway and SGK-1, with implications for Leishmania major (L. major) infection and house dust mite-induced asthma." (PMID 34572015, 2021). "On the other hand, downregulation of miR-133a has been detected in asthma and its upregulation is able to ameliorate airway remodeling through PI3K/AKT/mTOR signaling pathways by targeting IGFR1 (insulin-like growth factor I receptor." (PMID 32630692, 2020). "Zou and other researchers have reported that in asthma, Brahman-related genes play an essential role in maintaining airway inflammation and affecting the PI3K/Akt/mTOR pathway." (PMID 32595726, 2020). "The greater role of airway inflammation and remodeling driving severe asthma in women and the regulatory action of estradiol on activation of PI3K/Akt signaling pathway, suggests a possible gender specific function of mTOR inhibition." (PMID 32102344, 2020). "In summary, a mouse model of asthma was successfully established with OVA challenge, and administration of ketamine at a proper dosage induced MTOR phosphorylation, inhibited autophagy, suppressed inflammation, and attenuated OVA-induced asthma." (PMID 30729138, 2019). "Thus, we hypothesize that mTOR signaling is also playing a role in asthma disease onset." (PMID 28674387, 2017). "Inhibition of mTOR signaling has immunosuppressive effects on T cells, antigen-presenting cells, B cells, and NKT cells that participate in the pathogenesis of asthma." (PMID 29234390, 2017). "mTOR signaling occurs downstream of the PI3K-signaling cascade and is known to play a significant role in the pathogenesis of asthma." (PMID 29234390, 2017). "In summary, we have shown herein that treatment of allergic mice with rottlerin results in the inhibition of PKC δ and the subsequent disruption of a PI3K/Akt/mTOR/HIF-1α/VEGF module, thereby reversing all pathophysiologic symptoms of asthma." (PMID 24312355, 2013).
asthma (continued). "Inhibition of mTOR blocks the synthesis of vascular endothelial growth factor (VEGF), an angiogenesis factor that induces an asthma phenotype in mice." (PMID 22685525, 2012). "In asthma, activation of the PI3K/Akt/mTOR pathway promotes the proliferation of airway smooth muscle cells and airway epithelial cells, leading to airway thickening and narrowing, and modulation of Th2 cell proliferation, activation, and apoptosis that are central to the inflammatory environment." (PMID 39940325, 2025). "Second, many other pathways, such as PI3K/Akt/mTOR pathway, TLR4/MyD88/NF-κB pathway, and Wnt/β-catenin pathway, are involved in the regulation of airway inflammation and remodeling in asthma." (PMID 38168709, 2024). "Additionally, the use of the DEK-targeting aptamer DTA-64 has been shown to reduce OVA-induced airway remodeling in asthma through the modulation of various signaling pathways such as Smad2/3, Smad4, p38MAPK, ERK1/2, JNK, and PI3K/AKT/mTOR." (PMID 38274803, 2023). "In addition to the PI3K/AKT/mTOR pathway, the janus kinase (JAK) signalling pathway has been shown to play a key role in asthma." (PMID 35769905, 2022). "As such, the ultimate treatment for improving immune regulation and asthma could be to maintain the balance of Th1/Th2 cells, which depends on PI3K/mTOR activity." (PMID 35889810, 2022). "The top 10 highest degree of targets were EGFR, JAK1/2, MAPK14, VEGF, SRC, mTOR, PI3K, and GSK3B, which might be the critical targets of HHAE for the treatment of asthma." (PMID 36408342, 2022). "Moreover, inhibition of PI3K/Akt/mTOR and TLR4/MyD88/NF-κB signaling with targeted molecules can attenuate pathological mechanisms of asthma and play an important role in protecting airways against allergic response and inflammation pathology." (PMID 35444643, 2022). "PM2.5 counteracts with IL-4-induced M2 polarization partially through mammalian target of rapamycin (mTOR) pathway, whereas in ovalbumin (OVA)-induced asthma, PM2.5 aggravates allergic inflammation by activating M2 macrophages and subsequent Th2-related immune responses." (PMID 31067702, 2019). "Activated mTOR signaling participated in IgE-activated mast cells and lymphocytes in asthma, while no such data was reported for ASMC remodeling." (PMID 30781615, 2019). "In fact, administration of metformin or the mTOR inhibitor rapamycin, reduce mTOR activity and induce AMPK phophorylation that in turn perform lipid oxidation and enhance the formation of Tm cells after infection and increase Treg responses in asthma model." (PMID 28348562, 2017). "The levels of serum mTOR and cytokines in mice were measured by ELISA after asthma induction with or without budenoside or mTOR inhibitor treatment." (PMID 28674387, 2017). "Notably, mRNA-LNP vaccination in combination with an mTOR inhibitor reduced the CD8+ T cell response without affecting the vaccine-induced anti-allergic effect in the preventive model of asthma." (PMID 40985871, 2025). "Recent study demonstrated that allergen-initiated inflammation suppresses mTOR and induces autophagy in airway epithelial cells, resulting in the production of certain proallergic cytokines such as IL25, further promoting the type 2 response and eventually perpetuating airway inflammation in asthma." (PMID 35718777, 2022). "Thus, consistent with the context-dependent effects of rapamycin on inflammation, the timing of mTOR inhibition may be an important determinant of efficacy and toxicity in HDM-induced asthma." (PMID 22685525, 2012). "Furthermore, mechanical strain of airway smooth muscle induces HIF-1α-dependent VEGF expression via mTOR and ERK pathways, which may thereby contribute to angiogenesis in asthma." (PMID 22685525, 2012). "Similarly, metformin can also inhibit mTOR and could have the potential to inhibit SASP in asthma." (PMID 31849968, 2019).
asthma (continued). "We examined the airway sections from nonasthma controls and individuals with severe asthma for MTOR activation using phosphorylated serine 240/244 (phospho-RPS6), which regulates key MTOR-dependent signaling pathways in cell proliferation, cell size, and protein synthesis." (PMID 40446022, 2025). "Our study newly introduced that PI3K/Akt/mTOR signaling not merely diminished the effect of miR-15a-5p on Th1/Th2 balance in CD4+ T cells, but also undermined the impact of miR-29c-3p on ASMC proliferation, which expanded knowledge about asthma pathogenesis." (PMID 33223504, 2020).